HLA-DRA (major histocompatibility complex, class II, DR alpha)
Description:
An alpha chain of antigen-presenting major histocompatibility complex class II (MHCII) molecule. In complex with the beta chain HLA-DRB, displays antigenic peptides on professional antigen presenting cells (APCs) for recognition by alpha-beta T cell receptor (TCR) on HLA-DR-restricted CD4-positive T cells. This guides antigen-specific T-helper effector functions, both antibody-mediated immune response and macrophage activation, to ultimately eliminate the infectious agents and transformed cells. Typically presents extracellular peptide antigens of 10 to 30 amino acids that arise from proteolysis of endocytosed antigens in lysosomes. In the tumor microenvironment, presents antigenic peptides that are primarily generated in tumor-resident APCs likely via phagocytosis of apoptotic tumor cells or macropinocytosis of secreted tumor proteins. Presents peptides derived from intracellular proteins that are trapped in autolysosomes after macroautophagy, a mechanism especially relevant for T cell selection in the thymus and central immune tolerance. The selection of the immunodominant epitopes follows two processing modes: 'bind first, cut/trim later' for pathogen-derived antigenic peptides and 'cut first, bind later' for autoantigens/self-peptides. The anchor residue at position 1 of the peptide N-terminus, usually a large hydrophobic residue, is essential for high affinity interaction with MHCII molecules.
Synonyms: HLA-DRA1
Tractability: Small molecule: a structure with a bound ligand is known. Antibody: UniProt places it where antibodies can reach, with high confidence; its Gene Ontology location is reachable by antibodies, with high confidence; UniProt predicts a signal peptide or a membrane-spanning region. PROTAC: UniProt records ubiquitination sites on it; ubiquitination databases record sites on it.
Gene: Protein-coding gene on chromosome 6 (32,439,872 to 32,445,047, forward strand). Ensembl gene ENSG00000204287.
Subcellular location: Cell membrane; Endoplasmic reticulum membrane; Early endosome membrane; Late endosome membrane; Lysosome membrane; Autolysosome membrane
Pathways (Reactome):
Immune System: Co-inhibition by PD-1; Downstream TCR signaling; Generation of second messenger molecules; Interferon gamma signaling; MHC class II antigen presentation; Phosphorylation of CD3 and TCR zeta chains; Translocation of ZAP-70 to Immunological synapse
Gene Ontology:
Molecular function: MHC class II protein complex binding; peptide antigen binding; polysaccharide binding; protein binding; T cell receptor binding
Biological process: antigen processing and presentation of endogenous peptide antigen via MHC class II; antigen processing and presentation of exogenous peptide antigen via MHC class II; antigen processing and presentation of peptide or polysaccharide antigen via MHC class II; cognition; myeloid dendritic cell antigen processing and presentation; peptide antigen assembly with MHC class II protein complex; positive regulation of CD4-positive, alpha-beta T cell activation; positive regulation of CD4-positive, CD25-positive, alpha-beta regulatory T cell differentiation; positive regulation of memory T cell differentiation; positive regulation of T cell mediated cytotoxicity; regulation of T-helper cell differentiation; immune response; positive regulation of immune response; positive regulation of T cell activation; antigen processing and presentation
Cellular component: autolysosome membrane; cell surface; early endosome membrane; endoplasmic reticulum membrane; extracellular exosome; immunological synapse; late endosome membrane; lysosomal membrane; lysosome; MHC class II protein complex; plasma membrane; clathrin-coated endocytic vesicle membrane; endocytic vesicle membrane; ER to Golgi transport vesicle membrane; Golgi membrane; lumenal side of endoplasmic reticulum membrane; trans-Golgi network membrane; transport vesicle membrane; membrane
Genetic constraint (gnomAD): Loss-of-function variants: 8 observed, 22.87 expected, observed/expected ratio (o/e) 0.35, 90% interval 0.2 to 0.63. The upper end of that interval is the gene's LOEUF score, 0.63, which puts it in group 2 of 6, group 1 being the genes least tolerant of losing a copy. Missense variants: 248 observed, 327.58 expected, observed/expected ratio (o/e) 0.76, 90% interval 0.68 to 0.84. Synonymous variants: 101 observed, 120.48 expected, observed/expected ratio (o/e) 0.84, 90% interval 0.71 to 0.99.
Homologues: Orthologues: chimpanzee PATR-DRA (99% identical), macaque MAMU-DRA (95% identical), rabbit HLA-DRA (85% identical), pig HLA-DRA (83% identical), dog HLA-DRA (80% identical), rat RT1-Da (77% identical), guinea pig HLA-DRA (75% identical), mouse H2-Ea (68% identical). Paralogues in human: HLA-DPA1 (59% identical), HLA-DQA1 (54% identical), HLA-DOA (53% identical), HLA-DQA2 (52% identical), HLA-DMA (22% identical), HLA-DRB1 (22% identical), HLA-DRB5 (22% identical), HLA-DQB1 (22% identical), HLA-DQB2 (22% identical), HLA-DMB (20% identical), HLA-DPB1 (20% identical), HLA-DOB (20% identical), and 1 more.
Diseases named in the same sentence as HLA-DRA in open-access papers:
HLA-DRA is named in the same sentence as 155 diseases in open-access papers, as found by Europe PMC text mining. Sharing a sentence is not in itself a finding about the gene and the disease. The quoted sentences say what the papers report.
COVID-19 (27 papers, 2021 to 2024). A disease caused by infection with severe acute respiratory syndrome coronavirus 2. "As a key protein in the immune system, HLA-DRA is expressed by antigen-presenting cells, and it has been linked to bronchial epithelial cells in COVID-19." (PMID 38632526, 2024). "Interestingly, we also noticed that estrogen-induced the expression of many of the COVID-19 and asthma-related risk genes involving HLA-DRA, HLA-F, and HLA-DOB, which play an important role in the immune response." (PMID 39872660, 2024). "Furthermore, we found that the genes mediated by high levels of estrogen highly overlapped with the risk genes for COVID-19 and asthma diseases, involving HLA-DRA, HLA-F, and HLA-DOB." (PMID 39872660, 2024). "Based on our systematic review and temporal characterisation of gene expression profiles, we ascertained that the induction of MCEMP1 and the downregulation of HLA-DRA gene expression was most reliable for early prediction of severe COVID-19." (PMID 36801619, 2023). "This highlights that the early expansion of myeloid-derived suppressor cell gene signatures, particularly MCEMP1 and HLA-DRA, can be an early prognostic biomarker for COVID-19 disease severity." (PMID 36801619, 2023). "Single cell RNA sequencing revealed that the upregulation of MCEMP1 and downregulation of HLA-DRA transcripts in severe COVID-19 subjects were seen in CD14+ immune cell subsets, which are primarily myeloid lineage cells." (PMID 36801619, 2023). "The comparative transcriptomics analysis indicated MCEMP1, ETS1 and HLA-DRA as the most promising candidates in discriminating severe vs mild COVID-19 outcomes." (PMID 36801619, 2023). "Future prospective studies will also be needed to validate the sensitivity and specificity of using MCEMP1 and HLA-DRA expression levels in predicting severe COVID-19." (PMID 36801619, 2023). "Our results are also consistent with other studies demonstrating that HLA-DRA protein expression is significantly reduced in severe COVID-19 patients compared to mild COVID-19 patients." (PMID 36801619, 2023). "To assess the informativeness of MCEMP1, ETS1 and HLA-DRA throughout each phase of COVID-19, we examined the temporal dynamics of these transcripts before and after the nadir of respiratory function from the same study cohort." (PMID 36801619, 2023). "On the other hand, ETS1 and HLA-DRA, were differentially downregulated by 2.10 fold and 2.28 fold, respectively, in severe COVID-19 patients." (PMID 36801619, 2023). "In particular, MCEMP1 and HLA-DRA were found to be differentially expressed in severe COVID-19 patients as early as four days from nadir of respiratory function." (PMID 36801619, 2023). "In contrast, downregulation of genes encoding HLA class 2 (HLA-DRA, HLA-DPA1, HLA-DMA, DYNLL1) was found in COVID-19 ECs which was further confirmed by GSEA analysis." (PMID 37029220, 2023). "Elevated MCEMP1 and reduced HLA-DRA gene expression in CD14+ cells during the early phase of disease are prognostic of severe COVID-19." (PMID 36801619, 2023). "Monocytes from severe COVID-19 patients displayed decreased HLA-DRA and increased CD163 expression compared to healthy donors and mild COVID-19 patients, consistent with prior reports." (PMID 36466858, 2022). "If several evidences confirm that a hyperinflammatory signature characterizes monocytes from COVID-19 patients, other data prove that an immunosuppressive signature, defined by downregulation of HLA-DRA, ALOX5AP, and RETN, also exists." (PMID 35710943, 2022). "Differential expression analysis in the scRNA-seq revealed that MHC class II genes, such as HLA-DRB5, HLA-DPB1, HLA-DPA1, HLA-DRB1, and HLA-DRA, were downregulated in convalescent COVID-19 individuals." (PMID 35464396, 2022). "No increased IgM reactivities were seen to any antigen in subacute COVID-19 samples compared with controls, but there was higher IgM reactivity to both spike protein and HLA-DRA in the convalescent samples." (PMID 36065116, 2022).
COVID-19 (continued). "Taken together, these findings highlight that MCEMP1 and HLA-DRA could be useful early prognostic biomarker for severe COVID-19 but likely limited for prognosis of severe influenza and dengue." (PMID 36801619, 2023). "As the upregulation of MCEMP1 and downregulation of HLA-DRA are characteristic of myeloid-derived suppressor cells (MDSCs), the results indicated that an early expansion of MDSCs could be involved in severe COVID-19 progression and pathogenesis." (PMID 38257728, 2023). "Indeed, the combination of both MCEMP1 and HLA-DRA expression levels was able to distinguish patients who subsequently developed severe vs mild COVID-19." (PMID 36801619, 2023). "Unsurprisingly, the “near to epithelial cell” myeloid population shows higher COVID-19 signatures score and highly expresses multiple MHC Class I and II related genes, such as B2M, HLA-A, HLA-B, HLA-C, HLA-E, and HLA-DRA, which are associated with the interferon (IFN) response." (PMID 37120608, 2023). "However, in severe COVID-19 cases HLA-DRA and HLA-DRB1 expression was decreased, while HLA-DRB5 remained unaltered compared to healthy controls." (PMID 34108966, 2021). "Hence, peripheral blood MCEMP1 and HLA-DRA gene expression levels could be useful for early triaging of patients before severe COVID-19 disease progression." (PMID 36801619, 2023). "Expression levels of major histocompatibility complex class II molecules, including HLA-DRA, HLA-DRB5, HLA-DPA1, and HLA-DQB1, which are expected to be increased following MAC activation in the COVID-19 group, were found to decrease." (PMID 38441496, 2024). "The most consistent differentially regulated genes in peripheral blood of severe COVID-19 patients were MCEMP1, HLA-DRA and ETS1 across the 7 transcriptomics datasets." (PMID 36801619, 2023). "Unlike MCEMP1, which was exclusively differentially expressed in CD14+ cells, reduced expression of HLA-DRA could be detected more broadly across other myeloid cells, B cells, T cells, NK cells and platelets, indicating a global suppression of antigen presentation in severe COVID-19 patients." (PMID 36801619, 2023). "The downregulation of class II major histocompatibility complex gene HLA-DRA is observed in multiple cell types and in both PBMCs and BALF of severe COVID-19 patients, including myeloid cells, B cells, T cells, NK cells and platelets." (PMID 36801619, 2023). "This analysis confirmed previous reports of downregulation of HLA genes such as HLA-DRA and HLA-DRB5 in COVID-19 patients, with severe patients showing the most downregulation." (PMID 35007307, 2022). "Our DEG analysis showed increased levels of HLA-DRA, HLA-DRB1 and HLA-DRB5 in CD16+ monocytes from mild COVID-19 cases compared to healthy donors." (PMID 34108966, 2021). "HLA-DRA has emerged as a key target in immunotherapy, previously associated with an inflamed TME in tumors and various non-tumor diseases, including COVID-19, osteoarthritis, and dry eye syndrome." (PMID 39346909, 2024). "In contrast to COVID-19(+) TV, highly expressed in the COVID-19(-) PU control group included MHC class II antigen processing (HLA-DRB3/4, HLA-DPB1, HLA-DRA, CIITA, and CD74), mast cell degranulation (TPSAB1/B2), B cell activation (CXCL13, BLNK, IL-6) and histone modification (USP21, HIST1H4E)." (PMID 37026002, 2023). "We used a total of 7 publicly available RNAseq datasets, comprising of a total of 140 severe and 181 mild COVID-19 patients collected during the acute phase of SARS-CoV-2 infection, and uncovered that the top differential genes included MCEMP1, ETS-1 and HLA-DRA." (PMID 36801619, 2023). "Patients with COVID-19 showed downregulation of genes involved in the AP-1 transcription factor pathway (including JUN, JUNB, JUND, and FOSB) as well as HLA genes (including HLA-E, HLA-DRB1, HLA-DRA, and HLA-DPB1)." (PMID 36992700, 2023).
COVID-19 (continued). "Since severe COVID-19 is characterised by increased C Reactive Protein (CRP) and lymphopenia, which were used in several COVID-19 clinical severity scores, we correlated the abundance of MCEMP1, ETS1 and HLA-DRA transcripts to CRP and lymphocyte counts." (PMID 36801619, 2023). "Among the overlapping cell types, we found that 49% of ADT-annotated activated effector T cells cluster (HLA-DR+CD38+, ADT cluster #15) are overlapped with GEX dividing T/NK cluster, indicating expression of both HLADRA/CD38 and MKI67 marks a unique T cell subset in COVID-19." (PMID 35064122, 2022). "In contrast, genes involved in antigen presentation through MHC II presented a “valley” pattern, with under-expression among TUBE early compared to HLTY and COVID-19 compared to INFL, which strikingly predominated in TUBE early (e.g. HLA-DRA, HLA-DRB1, HLA-DQA1, CD74/Ii/CLIP/SLIP)." (PMID 34135895, 2021). "Post-COVID-19 monocytes showed “back-to-normal” expression features such as the downregulation of IL-10 and the upregulation of CD4 and HLA-DRA, which was in agreement with the flow cytometry data showing an increase of HLA-DR expression in monocyte surface after recovery." (PMID 34572439, 2021). "Further, we investigated the expression of MHC class II molecules (MHCII) and Fc receptors (FcRs) and found that they were broadly upregulated in APCs in lungs of mild COVID-19 patients, with a MHCII subset (HLA-DRA, HLA-DMB, HLA-DRB1, HLA-DPB1, HLA-DQB1, HLA-DMA) were downregulated." (PMID 34502134, 2021). "Also, HLA-DRA, HL-DMA, and HL-DMB decreased in COVID-19, especially in severe cases, consistent with Mudd PA’s result, who reported that abundances of HLA-DR of monocytes significantly reduced in COVID-19." (PMID 35573725, 2022). "Overall, our results indicate that reduced HLA-DRA can be detected in both peripheral blood and in BALF across multiple types of antigen-presenting cells, indicating that immunosuppression and reduced antigen-presentation could be critical early events involved in severe COVID-19 progression." (PMID 36801619, 2023).
Sepsis (25 papers, 2009 to 2025). Sepsis is defined as life-threatening organ dysfunction caused by a dysregulated host response to infection. "To find out the relevance of the imbalanced impact of ncRNAs to blood cells and/or liver transcripts, we sought for predicted targets of miR-608 that associate with MetS and/or sepsis reports, which highlighted its HLA-DRA target as uniquely related to both." (PMID 29922126, 2018). "Gene expression analysis revealed a sepsis-associated decreased transcription of (i) the classical HLA genes HLA-DRA, HLA-DRB1, HLA-DPA1 and HLA-DPB1 and (ii) the gene of the MHC-II master regulator, CIITA (Class II Major Histocompatibility Complex Transactivator)." (PMID 33939725, 2021). "In this study, we hypothesize that the mRNA expression level of HLA-DRA, measured by qPCR, is significantly associated with LPS-induced TNFα production in whole blood from patients with sepsis or septic shock." (PMID 28771573, 2017). "Prior studies have highlighted the importance of HLA-DRA as a promising future biomarker for evaluating immunosuppression in sepsis." (PMID 38166628, 2024). "In the GSE65682 dataset, CD3E (AUC:0.9509), HLA-DRA (AUC:0.974), IL2RB (AUC:0.9931), ITK (AUC:0.9727) and LAT (AUC:0.9575) showed good diagnostic efficiency in distinguishing sepsis patients from healthy controls." (PMID 38166628, 2024). "Experiments have confirmed that monitoring HLA-DRA by using qRT-PCR can help us to detect the dynamic changes in the immune state in sepsis, which is beneficial to future research." (PMID 37834169, 2023). "We exploited the expression profile of HLA-DRA and miR-222, a newly described marker of innate immunosuppression, as surrogates of immune competence for stratification of patients with sepsis or ACLF." (PMID 38106412, 2023). "The decreasing of macrophage-specific marker (MPEG1) and major histocompatibility complex, class II, DR alpha (HLA-DRA) in sepsis patients and ARDS patients were consistent with these findings." (PMID 37443002, 2023). "It was consequently concluded that combination of PCT with HLA-DRA holds promise as a mode for improving sepsis detection in surgical patients." (PMID 34945111, 2021). "Multivariate and AUC/ROC analysis showed that the PCT/HLA-DRA ratio was superior to PCT for the purpose of detection of sepsis with AUC of 0.85." (PMID 34945111, 2021). "In detail, transcription of genes encoding for HLA-DR subunits (HLA-DRA and HLA-DRB1) was strongly reduced in patients with postoperative sepsis (****p<0.0001 and ***p<0.001)." (PMID 33939725, 2021). "Depressed expression of HLA-DRA in monocytes and dendritic cells has been found in patients with sepsis, probably due to an increased apoptosis of lymphoid cells or T-cell exhaustion." (PMID 31500177, 2019). "In conclusion, our results support the combined quantification of PCT with that of HLA-DRA mRNA as a promising strategy for improving sepsis detection in surgical patients." (PMID 30097607, 2018). "Multivariate analysis demonstrated that the PCT/HLA-DRA ratio outperformed PCT in predicting sepsis." (PMID 30097607, 2018). "In conclusion, the combination of PCT with HLA-DRA is a promising strategy for improving sepsis detection in surgical patients." (PMID 30097607, 2018). "In contrast, HLA-DRA gene expression levels decreased with organ failure degree and the presence of sepsis." (PMID 30097607, 2018). "In detail, genes encoding for subunits of HLA-DR (HLA-DRA and HLA-DRB1) showed a lower expression in patients with HLA-DR suppressive sepsis (**p<0.01 and *p<0.05)." (PMID 30212590, 2018). "In this regard, the OOP identified for the PCT/HLA-DRA ratio improved the sensitivity of PCT to identify sepsis patients, preserving specificity." (PMID 30097607, 2018). "Area under the receiver operating curve analysis (AUROC) showed that the PCT/HLA-DRA ratio outperformed PCT to detect sepsis (AUROC [CI95%], p): PCT: 0.80 [0.73–0.88], <0.001; PCT/HLA-DRA: 0.85 [0.78–0.91], <0.001." (PMID 30097607, 2018).